INS (insulin)
Diseases named in the same sentence as INS in open-access papers (continued):
Sharing a sentence is not in itself a finding about the gene and the disease.
diabetes (continued). "For example, although early worsening of diabetic retinopathy was noted in a higher proportion of those assigned to intensive treatment in the Diabetes Control and Complications Trial (DCCT), the long-term benefits of intensive insulin treatment greatly outweighed the risks of this early worsening." (PMID 25945354, 2015). "Recent studies indicate that commonly used drugs in diabetes, including ACE inhibitors, DPP4 inhibitors, GLP-1 agonists, insulin, metformin, statins, or thiazolidinediones, may increase the number of EPCs and improve EPC function." (PMID 26077117, 2015). "Due to the high affinity to insulin, IGFBP7 may interfere with biological response of insulin, subsequently induces IR and involves in the development of diabetes and cardiovascular diseases." (PMID 25984973, 2015). "Diabetes mellitus is a global health problem affecting children, adolescents, and adults occurring when the pancreas does not produce enough insulin or/and when the body cannot effectively use the insulin produced by the pancreas." (PMID 26435566, 2015). "Insulin-stimulated GLUT4 expression is unalterably accompanied by excessive accumulation of adipose tissue, which is a life-threatening factor in major metabolic disorders such as obesity and diabetes." (PMID 26703529, 2015). "Recent observations suggest that diabetes treated or not with insulin has a different impact on mortality in advanced HF even after CRT." (PMID 25880202, 2015). "All the control subjects did not take any drugs, while the diabetes patients routinely took insulin and oral drugs (including hypoglycemia drugs, angiotensin-converting enzyme inhibitor/Angiotensin II receptor antagonist, statins)." (PMID 26517838, 2015). "In individuals without diabetes, dietary protein does not alter postprandial glycaemia, however, it stimulates a significant postprandial insulin response, which is required for amino acid uptake." (PMID 26202844, 2015). "Point accuracy did not meet the International Organization for Standardization (ISO) 14971 standard for insulin dosing accuracy but did improve with increasing numbers of calibrations and was better in patients who did not have a history of diabetes." (PMID 25652770, 2015). "Another study also reported an inverse association of Cr intake with fasting insulin level and several studies have reported benefits of chromium supplementation on insulin sensitivity in adults with or without type 2 diabetes mellitus." (PMID 25652875, 2015). "Log insulin dose was positively related with log adiponectin during early diabetes, but at 9 and especially 20 years a negative relationship emerged (P = 0.030 for interaction)." (PMID 25950008, 2015). "This association was attenuated and was no longer statistically significant when models were further adjusted for insulin, adiponectin, C-reactive protein, and estradiol and when additionally restricted to those without a history of diabetes." (PMID 26106415, 2015). "The liver response to insulin also improved by the end of week 1 so that insulin suppression of hepatic glucose output improved from a mean of 43% to 74%, the latter being similar to weight-matched controls without diabetes." (PMID 25159817, 2014). "The average of disease duration was longer in diabetes with insulin treatment than without insulin treatment (p<0.0001)." (PMID 25750761, 2014). "No significant statistical differences were noticed within WHR, blood pressure, blood lipid levels, coronary artery disease, diabetes, fasting insulin, or other locations of SLI between the depression and non-depression groups." (PMID 24752391, 2014). "In diabetes, removal of amino acids from plasma seems delayed and gluconeogenesis from amino acids in liver seems enhanced by the lack of proper suppression by insulin, thus contributing to hyperglycemia." (PMID 25106484, 2014). "None of the non-PDR participants had a history of diabetes mellitus and none had received insulin or laser treatment." (PMID 25401103, 2014).
diabetes (continued). "Although pramlintide is an available drug for diabetes, at late stage of diabetes most diabetes patients have insulin treatment only without receiving pramlintide." (PMID 25750761, 2014). "The concentration of plasmatic adiponectin was not affected by diabetes, but increased after insulin replacement." (PMID 25170835, 2014). "Additional adjustment for insulin therapy regimen, diabetes duration, region of residence, weight status and HbA1c (not for HbA1c outcome) affected estimates only little (data not shown)." (PMID 25384048, 2014). "Subjects were divided into insulin, tablet, combination therapy, and drug-naive groups together with a control group without diabetes." (PMID 24868461, 2014). "For non-critically-ill patients treated with insulin, according to the Standards of Medical Care in Diabetes 2013, the pre-meal glucose target should be around 140 mg/dL and post-meal glucose target should be around 180 mg/dL." (PMID 25259806, 2014). "To prove that plasma amylin was associated with cognition depending on the disease duration and severity, we used a homebound elderly population and divided it into three subgroups: 1) those without diabetes, 2) diabetics without and 3) with insulin treatment." (PMID 25750761, 2014). "Randomized controlled trials ≥3 weeks conducted in individuals with diabetes that compare the effect of diets emphasizing tree nuts to isocaloric diets without tree nuts on HbA1c, fasting glucose, fasting insulin, and HOMA-IR." (PMID 25076495, 2014). "A decrease in amotivation for taking insulin, checking blood sugar, and following diet and exercise regimes regularly indicates that GSD-Y adolescents began a process of becoming more engaged in their own diabetes management." (PMID 25118146, 2014). "As the Diabetes MILES survey did not ask participants to report previous diabetes treatments, we are unable to clarify what proportion, if any, were prescribed insulin immediately after diagnosis of T2DM." (PMID 24902877, 2014). "Specialist diabetes medical personnel are lacking as is the reliable provision of medicines and insulin." (PMID 25306156, 2014). "Although long-term hyperglycemia (glucose toxicity) deteriorates diabetes and irreversibly damages the viable BC that survived from STZ, the elimination of hyperglycemia with insulin injection if happens shortly after induction of diabetes prevents the diabetogenic effects of STZ." (PMID 24842144, 2014). "Diabetes is a condition that develops when the body does not produce or use a hormone called insulin effectively." (PMID 25233132, 2014). "Another small open study in 32 patients with both mild-to-moderate AD (or amnestic MCI) and diabetes mellitus not on insulin randomised patients between the PPARγ agonist pioglitazone or no additional treatment." (PMID 25385407, 2014). "Type 1 diabetes mellitus (T1D) is a chronic condition in which the pancreas produces little or no insulin due to autoimmune destruction of insulin-producing β cells in the islets." (PMID 24714958, 2014). "It is interesting that duration of diabetes does not seem to impair response, suggesting that the ability of DPP-4 inhibitors to augment meal associated insulin secretion does not decline with time of having diabetes." (PMID 25180036, 2014). "As an autosomal dominant inherited form of diabetes, MODY is caused by gene mutations leading to insufficient insulin production without or with minimal insulin resistance." (PMID 25136813, 2014). "Therefore, VOSO4 treatment normalized plasma glucose and insulin levels and improved insulin sensitivity in STZ-experimental diabetes and induced beta cells proliferation and/or regeneration in normal or diabetic rats." (PMID 25215302, 2014). "There are two main types of diabetes mellitus: Type 1, in which the body does not produce sufficient insulin; Type 2, due to the resistance to the insulin, often initially with normal or increased levels of circulating insulin." (PMID 25072200, 2014).
diabetes (continued). "In contrast, BB rats have no capacity to produce any insulin and develop an insulin-dependent diabetes resembling that in humans." (PMID 25216784, 2014). "A further limitation is the lack of information regarding the diagnosis of diabetes, use of oral hypoglycaemics or insulin in those included in the studies." (PMID 25526881, 2014). "Type 2 diabetes mellitus (T2DM) is a metabolic disorder characterized by chronic hyperglycemia with disturbances of carbohydrate, lipid and protein metabolism resulting from defects in insulin secretion, insulin resistance, or both." (PMID 25399255, 2014). "Diabetes is characterized by high blood glucose level due to either autoimmune destruction of islet β-cells or insufficient insulin secretion or glucose non-responsive production of insulin by β-cells." (PMID 24594290, 2014). "Recent studies have shown that mutations in human KLF11 gene or KLF11 binding element in the human insulin promoter, which impairs KLF11 binding to promoter and activation of insulin gene promoter, results in diabetes leading to decreased human insulin biosynthesis." (PMID 24586865, 2014). "Diabetes is a disease characterized by chronic hyperglycemia resulting from impaired carbohydrate metabolism with an absolute or relative lack of insulin." (PMID 24993916, 2014). "We propose that the GF NOD mice are more resistant to developing diabetes because lower levels of insulin are required to maintain normoglycaemia in these mice." (PMID 25390735, 2014). "The plasmatic concentration of the secreted protein was not altered by diabetes but increased in response to insulin replacement." (PMID 25170835, 2014). "All multiple regression analyses were adjusted for age, gender, education, duration of diabetes, treatment with insulin (yes/no) and other chronic disease (yes/no)." (PMID 24367063, 2014). "However, the Diabetes Control and Complications Trial/Epidemiology of Diabetes Intervention and Complication (DCCT/EDIC) study indicated that intensive treatment with insulin had long-term positive effects on CVD in patients with type 1 diabetes mellitus." (PMID 24607023, 2014). "In Zucker diabetic fatty rats, combination treatment of JTT-130 and pioglitazone showed better glycemic control and a strong hypolipidemic action with an enhancement of insulin sensitivity." (PMID 24772450, 2014). "The bias in internal validity is most likely attributed to the misclassification of diabetes outcomes that only rely on self-reporting the prevalence of T2DM, the use of oral antidiabetic drugs or insulin, or that patients were on a specific diet but lack of an accurate fasting glucose." (PMID 25329153, 2014). "Distinction between patients with diabetes treated with only OHAs and with insulin was hampered by the small numbers, and the lack of differences between these groups should be taken with reservation." (PMID 25139960, 2014). "In the CRF only the presence of drugs for the treatment of dyslipidemia and diabetes (oral and insulin) were recorded, but no specific drugs nor those in particular with an interaction potential on serum potassium." (PMID 25480344, 2014). "Some of the currently used anti-diabetics include oral [e.g., biguanides, sulfonylureas (SUs), thiazolidinediones (TZDs), and dipeptidyl peptidase-IV (DPP-IV) inhibitors] and injectable agents (e.g., insulin and GLP-1 analogs)." (PMID 25071725, 2014). "Type 1 diabetes mellitus, which is characterized by a lack of insulin production, accounts for 5–10% of diabetes and a peak incidence occurs at 10–14 years of age." (PMID 25289023, 2014). "These alterations begin early, after 15 days of diabetes induction and are not prevented by conventional insulin treatment." (PMID 24387617, 2014). "In summary, we have found that WSB mice have interesting diabetes-related phenotypes that are not widely studied, including reduced pancreatic growth, and markedly increased insulin secretion in vitro." (PMID 24505481, 2014).
diabetes (continued). "In the past, diabetes was often divided into “insulin-dependent diabetes” and “insulin-independent” diabetes; terms that are not generally used in the medical community today." (PMID 24919660, 2014). "Since neurons and capillaries' membranes are not insulin dependent in transporting glucose, great amount of glucose enters cells in diabetes." (PMID 25614895, 2014). "Diabetes is a common condition where sugar (glucose) levels of the body are poorly regulated, due to either lack of production of the hormone insulin, made in the pancreas, or an increase in resistance of tissues in the body to the effects of insulin." (PMID 26401325, 2014). "As expected, pretreatment with ES-DC-TRAIL/insulin and -TRAIL/GAD65 significantly inhibited the development of diabetes compared with non-treated control NOD mice, and ES-DC-TRAIL also suppressed the development of diabetes." (PMID 25522369, 2014). "Quality of life was significantly associated with three factors that interacted with each other: diabetes duration, treatment with insulin, and the presence or absence of DR." (PMID 25138117, 2014). "In diabetes, the sorbitol pathway increases in activity in tissues like retina, kidney, peripheral nerves, and blood vessels where insulin is not required for cellular glucose uptake." (PMID 25105142, 2014). "In diabetes mellitus and insulin resistance, insulin-mediated activation of eNOS viaPI3 kinase/AKT1 is inhibited, while the adverse effects of insulin remain unopposed, which may promote vascular disease." (PMID 24734227, 2014). "Fasting blood glucose, fasting insulin and lipid profiles should be assessed and oral glucose tolerance testing (OGTT) should be performed in the presence of additional risks (family history of diabetes or acanthosis nigricans, etc.)." (PMID 24932597, 2014). "In people with diabetes, blood sugar control fails because they make no insulin (type 1 diabetes) or because the cells that normally respond to insulin by removing sugar from the blood have become insulin-resistant (type 2 diabetes)." (PMID 25289645, 2014). "Diabetes mellitus type 2 is a metabolic disorder that is characterized by hyperglycemia in the context of insulin resistance and lack of insulin." (PMID 25375187, 2014). "In Korea, previous studies reported that approximately 65% of subjects with diabetes were non-obese, and that impaired insulin secretion was more prominent than insulin resistance in diabetic subjects." (PMID 25530810, 2014). "As expected, levels of circulating insulin decreased in both the NOD and STZ model of diabetes." (PMID 25101835, 2014). "Insulin administration prevented albuminuria, markedly reduced GFR, blood pressure, and glomerular enlargement in the early stage; and prevented mesangial expansion and the reduced podocyte number in the late stage of diabetes." (PMID 24400109, 2014). "Compared to non-diabetics, diabetes with insulin treatment had a lower, but those without insulin treatment had a higher, average concentration of plasma amylin." (PMID 25750761, 2014). "After FC I/R injury, diabetic rats showed a dramatic enhancement of peroxynitrite production compared with non-diabetic controls, and the diabetes-induced peroxynitrite level increase was significantly attenuated by insulin treatment." (PMID 25223305, 2014). "The neogenesis of insulin-producing cells (IPCs) from non-beta-cells has emerged as a potential method for treating diabetes mellitus (DM)." (PMID 25006589, 2014). "These mutants show no signs of diabetes; they are extremely insulin sensitive with low levels of glucose and insulin in circulation." (PMID 24690289, 2014). "That of HSL was not altered by diabetes, was significantly reduced by insulin treatment in eWAT and rWAT but increased in scWAT." (PMID 25170835, 2014). "All forms of diabetes are characterized by hyperglycemia, insulin resistance, relative or absolute lack of insulin action, and the development of diabetes specific pathology in the retina." (PMID 25105142, 2014).
diabetes (continued). "In T2D, in a study of 18 patients who had been hospitalized to initiate insulin therapy because of poor diabetes control, CRP values, but not MCP1 and fibrinogen levels, were decreased 2 weeks after initiation of insulin therapy." (PMID 24495560, 2014). "It is plausible that the differences in the prevalence of diabetes between men and women are due to the fact that nondiabetic men are generally more insulin-resistant than women." (PMID 25548563, 2014). "Insulin therapy and oral antidiabetic agents/drugs used in the treatment of diabetes mellitus have not sufficiently proven to control hyperlipidemia." (PMID 25525518, 2014). "Maternal obesity likely contributes to macrosomia via mechanisms including increased insulin resistance (even in women who do not have diabetes) resulting in higher fetal glucose and insulin levels." (PMID 25544943, 2014). "We examined the association between weight trajectories and higher glucose, HbA1c, HOMA-IR and insulin levels in 2009, but we do not know when elevations in these diabetes markers first developed." (PMID 24891020, 2014). "BCL11A has been associated with type 2 diabetes mellitus, but prior work has not linked BCL11A to insulin regulation in mammals." (PMID 25101872, 2014). "Among patients with type 1 diabetes mellitus (T1DM), insulin self-titration is already well-established suggesting that therapeutic self-management may be similarly beneficial when applied to patients with T2DM." (PMID 25340869, 2014). "In the STZ model of experimental diabetes it has been reported that VEGF expression increased in DRG and sciatic nerves and that insulin and/or nerve growth factor administration could prevent it." (PMID 25268360, 2014). "This also explains how an absence of coupling elevates [Ca2+]i and insulin release to prevent the progression of diabetes." (PMID 25188228, 2014). "It is possible that this improvement in control of diabetes is reflected in mental health, although the current study did not specifically examine the use of insulin pumps." (PMID 25303963, 2014). "Type 1 diabetes mellitus (T1DM) is an autoimmune disease where adaptive immunity-mediated destruction of pancreatic β cells leads to an absolute absence of insulin." (PMID 25548690, 2014). "Furthermore, it seems conceivable to use therapeutic interventions, such as insulin, to try to reverse the impaired response to an AMI of diabetics and possibly improve the dismal prognosis of these patients." (PMID 24934236, 2014). "Despite the high prevalence of diabetes in Turkey, most primary care physicians rarely initiate, modify or intensify insulin therapy, with the lack of experience and time to educate patients often being cited as the main barriers." (PMID 25048824, 2014). "According to our study, diabetes is protective in ALI/ARDS, then reversal of the anti-inflammatory effects of diabetes by insulin may negate the beneficial effect of diabetes on ALI/ARDS." (PMID 24587357, 2014). "We aimed to evaluate the predictive utility of common fasting insulin sensitivity indices, and non-laboratory surrogates [BMI, waist circumference (WC) and waist-to-height ratio (WHtR)] in sub-Saharan Africans without diabetes." (PMID 25106496, 2014). "Knowledge of insulin use is poor among insulin requiring patients with diabetes, with majority not conversant with such terms as ketoacidosis, insulin reaction and low blood sugar." (PMID 24397956, 2014). "Insulin-independent pathways to stimulate glucose uptake and GLUT4 translocation may offer alternative therapeutic avenues for the treatment of diabetes." (PMID 24849570, 2014). "In the group of patients without DR who were not receiving insulin therapy, treatment satisfaction increased as the duration of diabetes increased." (PMID 25138117, 2014). "It was reported from early studies that infusion of l-arginine increases insulin release, and this is disrupted in patients with non-insulin-dependent diabetes mellitus (NIDDM)." (PMID 25705631, 2014).